RNU6-2 (RNA, U6 small nuclear 2)
Synonyms: U6-2; RNU6B; RP104
Gene: Small nuclear RNA gene on chromosome 19 (1,021,522 to 1,021,628, forward strand). Ensembl gene ENSG00000207357.
Gene Ontology:
Molecular function: U4 snRNA binding
Biological process: formation of quadruple SL/U4/U5/U6 snRNP; spliceosomal tri-snRNP complex assembly
Cellular component: U4/U6 x U5 tri-snRNP complex; U6 snRNP
Homologues: Orthologues: chimpanzee U6 (100% identical), dog U6 (100% identical), macaque U6 (100% identical), mouse Gm24205 (100% identical), rabbit U6 (100% identical). Paralogues in human: RNU6-1 (100% identical), RNU6-3P (100% identical), RNU6-4P (100% identical), RNU6-5P (100% identical), RNU6-6P (100% identical), RNU6-9 (100% identical), RNU6-12P (99% identical), RNU6-13P (99% identical), RNU6-17P (99% identical), RNU6-18P (99% identical), RNU6-25P (99% identical), RNU6-32P (99% identical), and 1288 more.
Diseases named in the same sentence as RNU6-2 in open-access papers:
RNU6-2 is named in the same sentence as 3 diseases in open-access papers, as found by Europe PMC text mining. Sharing a sentence is not in itself a finding about the gene and the disease. The quoted sentences say what the papers report.
tumour (1 paper, 2020). "Therefore, the low (and not significant) overexpression values of miR-1271 in ccRCC may have been due to increased expression of RNU6-2 in the tumour." (PMID 33277569, 2020).
RNU6-2 also shares sentences with these, for which no sentence is quoted: amyotrophic lateral sclerosis (1 paper); infection (1).